TLR9 (toll like receptor 9)
Diseases named in the same sentence as TLR9 in open-access papers (continued):
Sharing a sentence is not in itself a finding about the gene and the disease.
hepatocellular carcinoma (37 papers, 2011 to 2025). A malignant tumor that arises from hepatocytes. "Similar data were reported for hepatocellular carcinoma, where TLR9 expression on tumour-associated fibroblasts was associated with reduced overall survival." (PMID 28300057, 2017). "The present study aimed to investigate the temporal relationship of single nucleotide polymorphisms (SNP) of TLR2/TLR9 and the risk of hepatocellular carcinoma (HCC)." (PMID 22309608, 2012). "Furthermore, high TLR9 expression has previously been associated with a reduced OS rate in glioblastoma and hepatocellular carcinoma." (PMID 38850110, 2024). "Depleting cytoplasmic mtDNA via deoxyribonuclease I (DNase I) or blocking the TLR9 pathway via the TLR9 antagonist significantly decreased the recruitment and polarization of TAMs in overexpressed dynamin-related protein-1 (Drp1) hepatoma cells." (PMID 35326602, 2022). "For example, in hepatocellular carcinoma, TLR9 agonist treatment decreased PARylation of STAT3 and expression of PARP-1." (PMID 36077221, 2022). "Subsequent murine studies showed additive treatment effects of a TLR9 agonist in combination with anti-PD-1 or anti-PD-L1 therapy in hepatoma cell lines and HCC." (PMID 34025657, 2021). "Microarray analysis demonstrates that TLR7 and TLR9 are overexpressed in human hepatocellular carcinomas (HCCs) compared with liver tissues from cirrhotic and viral hepatitis patients." (PMID 27456065, 2016). "It has also been demonstrated that cell surface stimulation of TLR9 promotes cell proliferation and survival in hepatocellular carcinoma." (PMID 21929816, 2011). "We further demonstrated that histone H3 could also promote proliferation and metastasis of hepatocellular carcinoma through TLR9 activation of NLRP3 inflammasome." (PMID 37082731, 2023). "We found that hypoxia could contribute to this phenomenon of histone H3 translocation from the nucleus to the cytoplasm in hepatocellular carcinoma cells and increased binding levels to TLR9." (PMID 37082731, 2023). "Moreover, the same study showed that HMGB1 activates the TLR9 signaling pathway by binding to released mtDNA to trigger inflammation and promote tumor growth in hepatocellular carcinoma during hypoxia." (PMID 32155899, 2020). "In a cell line of hepatocellular carcinoma, TLR-9 activation increases proliferation and inflammation by up-regulating IL-8, IL-1, IL-6, inhibits apoptosis and in esophageal cells stimulates invasion by inducing the expression of matrix metalloproteinase 2 (MMP-2), MMP-7 and cyclooxygenase-2 genes." (PMID 28548068, 2014). "Moreover, TLR9 mRNA and protein were downregulated in PBMCs from patients with HBV-associated chronic hepatitis and hepatocellular carcinoma." (PMID 22046272, 2011). "In hepatocellular carcinoma (HCC), mtDNA released from the extracellular matrix activates TLR9 signaling, triggering inflammatory responses." (PMID 41154678, 2025). "Further studies showed that during hypoxia, nuclear HMGB1 translocate to the cytoplasm and binds to mtDNA, which then activates TLR9 signaling and tumor proliferation in hepatocellular carcinoma (HCC)." (PMID 35209954, 2022). "Research found genetic ablation of TLR9 reduced idiopathic liver injury, fibrosis and hepatocellular carcinoma (HCC) in hepatic deletion of TGF-β-activated kinase 1 (Tak1ΔHep) mice." (PMID 35006454, 2021). "Analysis of PBMC from chronic hepatitis B and HBV-associated hepatocellular carcinoma patients suggest that TLR9 mRNA levels are downregulated in CHB and that TLR9 protein is drastically reduced in both CHB and HCC patients." (PMID 22046272, 2011). "In Hepatocellular Carcinoma (HCC) research, TLR9 agonists have been shown to upregulate PD-L1 expression, which can ultimately induce immune escape." (PMID 41488647, 2025). "In hepatocellular carcinoma (HCC), the activation of TLR4 and TLR9 by NETs led to upregulation of cyclooxygenase-2 (COX2), which enhanced the invasiveness of tumor cells." (PMID 37958984, 2023).
hepatocellular carcinoma (continued). "Another example is in hepatocellular carcinoma, where the activation of TLR4 and TLR9 by NETs led to upregulation of COX2, a potent inflammatory mediator, which enhanced the invasiveness of HCC cells." (PMID 36050539, 2023). "Under hypoxic conditions, HMGB1 could mediate the binding of mtDNA and TLR9, thereby activating the protumorigenic signaling pathways to promote the growth and metastasis of hepatocellular carcinoma cells (HCC)." (PMID 35454769, 2022). "Recent studies indicated that stimulation of TLR9 with CpG-ODN enhanced apoptosis in murine or human tumor cells, but ODN M362 promotes cell proliferation and survival in human hepatocellular carcinomas." (PMID 24161202, 2013). "Furthermore, TLR9 activation induces tumorigenesis and immune escape via PD-L1 upregulation in OSCC and hepatocellular carcinoma." (PMID 38850110, 2024). "Mitochondria of hepatocellular carcinoma cells release mtDNA into the cytoplasm in response to ROS, activating Toll-like receptors (TLRs), of which TLR9 can induce CCL2 to recruit macrophages to the TME.Additionally, TLR9 activation can also contribute to the maintenance of the M2 phenotype of TAMs." (PMID 37545527, 2023). "In hepatocellular carcinoma (HCC) cells, Drp1-dependent division aguments mtDNA stress and thus enhances the secretion of CCL2 via the TLR9-involved NF-κB pathway." (PMID 37497006, 2023). "In hepatocellular carcinoma (HCC) tumors, HMGB1 was shown to mediate tumor growth, under hypoxic conditions, through the interaction with intracellular TLR-9 and to attract macrophages to the tumor site, resulting in increased metastasis." (PMID 34360919, 2021). "TLR9 expression and function in BEL-7402 cells, belong to the human hepatoma cell lines, are not reported." (PMID 24161202, 2013).
atherosclerosis (34 papers, 2015 to 2025). A disease characterized by the build-up of fatty material and calcium deposition in the arterial wall resulting in partial or complete occlusion of the arterial lumen. "Loss of TLR9 function thus exacerbates atherosclerosis in ApoE null mice exposed to a high fat diet." (PMID 27795867, 2016). "Additionally, drug intervention focusing on blocking TLR9 hampers the progression of atherosclerosis progression, supporting the notation that TLR9 is associated with atherosclerosis." (PMID 36093338, 2022). "In the development of atherosclerosis, TLR9 activation in immune cells, particularly macrophages, triggers the production of pro-inflammatory cytokines." (PMID 40867523, 2025). "The upregulation of CD73 with agents, including AGT-5, Aire-overexpressing DCs, Aspirin, BAFFR-Fc, CD4+ peptide, ICAs, IL-2 therapies, SAgAs, sCD73, stem cells, RAD51 inhibitor, TLR9 inhibitor, and VD, decreased diabetes and atherosclerosis development." (PMID 39735551, 2024). "TLR9 activation can also suppress angiogenesis, impair endothelial regeneration, and promote atherosclerosis." (PMID 33138323, 2020). "In an atherosclerotic mouse model, TLR9 promotes the production and secretion of pro‐inflammatory factors extensively, triggering the inflammatory reaction and promoting the occurrence of atherosclerosis." (PMID 33140921, 2020). "Another issue to be further explored is the involvement of TLR receptors in atherosclerosis, being TLR9 a first candidate for future studies." (PMID 33664731, 2020). "On the other hand, several groups have reported incongruous findings which suggested protective roles of TLR9 in atherosclerosis." (PMID 32714475, 2020). "Monocyte/macrophages (M/Ms), activated by LPS, promote osteoblastic differentiation and mineralization of calcifying vascular cells (CVCs), while bacterial DNA/TLR9 signaling promotes atherosclerosis and vascular endothelial injury." (PMID 31007833, 2019). "LL37-mitochondrial DNA complexes were found to be enriched in plasma and atherosclerotic plaques in a mouse model of atherosclerosis; such complexes were also found to induce TLR9-mediated inflammatory responses." (PMID 30833557, 2019). "Recent studies showed that TLR9 activation promotes atherosclerosis, vascular endothelial injury, macrophage lipid accumulation, and myocardial dysfunction, suggesting a close relationship between TLR9 signaling and inflammatory vascular diseases." (PMID 31007833, 2019). "CD4+ T-cell depletion in these mice reduced atherosclerosis, suggesting a role of TLR9 in regulating CD4+ T cells in atherosclerosis." (PMID 28405010, 2017). "In Apoe−/− mice on a chow diet, TLR9 antagonist reduced aortic root atherosclerosis with decreased lesion inflammatory cell accumulation and increased lesion collagen and SMCs64." (PMID 28405010, 2017). "This review outlines the pathophysiological role of TLR2, TLR4, and TLR9 in atherosclerosis, focusing on evidence from animal models of the disease." (PMID 27795867, 2016). "The subsequent sections of this review focus on the roles of TLR2, TLR4, and TLR9 in the pathogenesis of atherosclerosis." (PMID 27795867, 2016). "The precise function of TLR9 in atherosclerosis is yet to be defined, with conflicting studies reporting both proatherogenic and antiatherogenic effects." (PMID 27795867, 2016). "Our findings were partially substantiated by the reports that the antagonists of TLR7 and TLR9 reduced postinterventional remodeling by preventing neointima formation and accelerated atherosclerosis and chloroquine (a TLR9 inhibitor) induced atheroprotection." (PMID 26257462, 2015). "Most studies hitherto have focused on the implications of TLR4 or TLR2 on atherosclerosis, while the data on the roles of TLR9 in atherosclerosis is scarce." (PMID 26257462, 2015). "To investigate the mechanism by which TLR9 modulates atherosclerosis, we analyzed M1/M2 macrophage polarization in plaques." (PMID 26257462, 2015).
atherosclerosis (continued). "Our data showed that TLR9 inhibition in ApoE−/− mice displayed a modest decrease (34.9% in aortic root and 23.0% in the whole aorta tree) in the extent of atherosclerosis." (PMID 26257462, 2015). "Our data indicated that TLR9 inactivation ameliorated atherosclerosis via skewing macrophage plasticity to M2 phenotype in ApoE-deficient mice." (PMID 26257462, 2015). "This study aimed to investigate the role of TLR9 in atherosclerosis development and macrophage polarization." (PMID 26257462, 2015). "They concluded ECV can elevate level of damaged mitochondrial DNA in circulating blood and induce the expression of toll-like receptor 9 (TLR9), thereby increasing the expression of proinflammatory cytokines in monocyte/macrophage, which is responsible for atherosclerosis." (PMID 38376568, 2024). "The upregulation of CD73 with agents, including AGT-5, Aire-overexpressing DCs, Aspirin, BAFFR-Fc, CD4+ peptide, ICAs, IL-2 therapies, SAgAs, sCD73, stem cells, RAD51 inhibitor, TLR9 inhibitor, and VD, decreased the development of diabetes and atherosclerosis in preclinical trials." (PMID 39735551, 2024). "For example, miR-342-5p was found to suppress PI3K/AKT in classically active macrophages and act anti-inflammatory in an atherosclerosis plaque mouse model, and in an acute kidney injury model, exosomes loaded with miR-342-5p alleviated inflammation by targeting TLR9 to promote autophagy." (PMID 39569198, 2024). "In addition, Jieduquyuziyin prescription was also effective in alleviating atherosclerosis symptoms, mainly by regulating cholesterol efflux and inhibiting TLR9/MyD88 activation." (PMID 38952541, 2024). "A similar model of e-cigarette induced atherosclerosis showed that damaged mitochondrial DNA in circulating blood may produce the increase of Toll-like receptor 9 (TLR9), leading to increased pro-inflammatory cytokines and macrophages activation." (PMID 35463745, 2022). "Furthermore, TLR9 plays a crucial role in the development of vascular inflammation through proinflammatory activation of macrophages in angiotensin II-induced atherosclerosis via MyDD8 pathway." (PMID 36093338, 2022). "Further investigations are needed to clarify the effects of TLR9 on atherosclerosis." (PMID 36176986, 2022). "Electronic cigarette use has also been demonstrated to raise the level of mitochondrial cfDNA in the blood and induce the expression of TLR9, both of which increase the expression of proinflammatory cytokines in monocytes and macrophages and thereby contribute to the development of atherosclerosis." (PMID 36359370, 2022). "Atherosclerosis is also related to the cfDNA-mediated TLR9-signaling." (PMID 36359370, 2022). "Additionally, pharmacological inhibition of TLR9 can attenuate the e-cigarettes exacerbated atherosclerosis in ApoE KO mice." (PMID 35463745, 2022). "TLR9 signaling is important in myocardial infarction, atherosclerosis, and cancer immunotherapy." (PMID 34281221, 2021). "In addition, TLR9 gene deletion aggravated the atherosclerosis of ApoE−/− mice fed with high-fat-diet (HFD) and a TLR9 agonist reduced the severity of the disease." (PMID 32002588, 2020). "The role of TLR9 responses in atherosclerosis remains inconclusive." (PMID 29858401, 2018). "TLR3 activation has been found to promote atherogenic inflammation, especially in mediating plaque instability, while the absence of TLR9 exacerbates atherosclerosis in ApoE-deficient mice on a high-fat diet." (PMID 28769820, 2017). "However, our data is in contrast to the report that genetic deletion of TLR9 exacerbates atherosclerosis and TLR9 exerts atheroprotection in ApoE−/− mice." (PMID 26257462, 2015). "Therefore, we hypothesized that TLR9 plays a role in the development of atherosclerosis through the recognition of DNA fragments released by vascular damage." (PMID 32714475, 2020).
atherosclerosis (continued). "Therefore, in the present study, we aimed to determine whether TLR9 signaling can directly regulate the macrophage polarization and promote the progression of atherosclerosis." (PMID 26257462, 2015). "This review article aims to describe the immunological role of TLRs in promoting the development of atherosclerosis, with a primary focus on the function of TLR2, TLR4, and TLR9." (PMID 27795867, 2016). "Furthermore, the activation of pattern recognition receptors, such as Toll-like receptor 9 (TLR9), by endogenous ligands in SLE exacerbates inflammation and accelerates atherosclerosis progression." (PMID 40867523, 2025). "NETs impair wound healing under diabetic conditions by suppressing the toll-like receptor 9 (TLR9)-p21-activated kinase 2 (PAK2)-dependent Hippo-YAP signaling pathway and development of atherosclerosis by inducing TLR9/NF-κB-mediated interleukin-8 (IL-8) secretion in macrophages." (PMID 41008570, 2025). "Indeed, several animal studies have suggested that the administration of inhibitors for DNA sensors including TLR9 and STING attenuates the development of several lifestyle-related diseases such as insulin resistance, hepatic diseases, and atherosclerosis." (PMID 36176986, 2022). "All these observations, regardless of diet types, point to a detrimental role of TLR9 in atherosclerosis." (PMID 28405010, 2017). "Obviously, the use of different diets may not explain all the discrepancies in the role of TLR9 in atherosclerosis and additional mechanisms may be involved and merit further investigation." (PMID 28405010, 2017). "However, the direct evidence for the effect of blocking TLR9 on accelerated atherosclerosis is lacking." (PMID 26257462, 2015).
prostate carcinoma (34 papers, 2008 to 2026). A carcinoma that arises from epithelial cells of the prostate gland. "We observed that systemic CPG-1668 administration suppressed orthotopic prostate cancers, and this was associated with enhanced systemic immunity, supporting the utility of TLR9 agonists as a therapeutic strategy for prostate cancer." (PMID 38201300, 2024). "Increased expression of tumor-specific TLR9 has been associated with higher tumor grade and poor prognosis in patients suffering from breast, ovarian, or prostate cancer." (PMID 38201300, 2024). "In summary, our results demonstrated that overexpression of TLR9 was associated with a higher probability of lymph node metastasis and poor prognosis of prostate cancer." (PMID 26087186, 2015). "Using a cohort of 186 prostate cancer samples and their associated clinical data, this study showed that high TLR9 expression in tumor cells is an independent marker of poor prognosis in prostate cancer." (PMID 23761830, 2013). "A high level of TLR9 expression in prostate cancer tumor cells was also shown to be significantly associated with a higher probability of biochemical recurrence." (PMID 23761830, 2013). "In conclusion, this study shows that increased expression of TLR9 is associated with poor prognosis in prostate cancer." (PMID 23761830, 2013). "Expression of TLR9 is associated with poor progression-free survival in prostate cancer patients who were treated by radical prostatectomy with curative intent." (PMID 23761830, 2013). "Additionally, toll-like receptors (TLRs), particularly TLR4 and TLR9, have been implicated in prostate cancer invasion and metastasis." (PMID 40260236, 2025). "Similarly, several studies have revealed an association between TLR9 overexpression in tumor cells and poor prognosis in patients with prostate carcinoma and glioblastoma." (PMID 28116318, 2016). "A high level of TLR9 expression in prostate cancer cells was shown to be significantly associated with a higher Gleason score, a greater probability of biochemical recurrence and poor progression-free survival in patients who were treated by radical prostatectomy." (PMID 26087186, 2015). "Furthermore, in clinical breast, ovarian and prostate cancer specimens, increased TLR9 expression was associated with decreased tumour differentiation." (PMID 21929816, 2011). "According to our results, high level of TLR9 expression was significantly correlated with a higher probability of lymph node metastasis, which has been documented to be associated with poor prognosis, suggesting TLR9 involving in the metastasis of prostate cancer." (PMID 26087186, 2015). "It has also been reported that TLR9 expression in prostate cancer, promotes immune evasion through LIF mediated polymorphonuclear MDS activation and amplification." (PMID 41601666, 2026). "TLR9 was initially believed to be expressed exclusively in immune cells; however, recent evidence indicates that functional TLR9 is also present in various tumor types, including prostate cancer." (PMID 41601666, 2026). "TLR9 can be both tumor promoting and tumor suppressive in prostate cancer, and TLR9 is a marker for poor prognosis." (PMID 41601666, 2026). "All together this shows that NOB treatment alone has a greater anti-inflammatory effect on the inhibition of both the TLR4/TRIF/IRF3 and TLR9/IRF7 signaling pathways in prostate cancer than when combined with LPS or CpG-ODN treatment." (PMID 41601666, 2026). "For instance, a previous study demonstrated that TLR‐9 enhanced prostate cancer progression by augmenting the immunosuppressive effect of PMN‐MDSCs." (PMID 39947253, 2025). "Through polymorphonuclear MDSC proliferation and activation mediated by LIF (an IL-6 type cytokine and STAT3 activator), TLR9 expression in prostate cancer cells facilitates immune evasion." (PMID 40727443, 2025).